LCN8 (lipocalin 8)
Description:
May play a role in male fertility. May act as a retinoid carrier protein within the epididymis.
Synonyms: LCN5; EP17
Tractability: Antibody: UniProt places it where antibodies can reach, with medium confidence; UniProt predicts a signal peptide or a membrane-spanning region; its Gene Ontology location is reachable by antibodies, with medium confidence.
Gene: Protein-coding gene on chromosome 9 (136,754,386 to 136,758,543, reverse strand). Ensembl gene ENSG00000204001.
Subcellular location: Secreted
Gene Ontology:
Molecular function: small molecule binding
Cellular component: extracellular region
Genetic constraint (gnomAD): Loss-of-function variants: 16 observed, 22.26 expected, observed/expected ratio (o/e) 0.72, 90% interval 0.49 to 1.09. The upper end of that interval is the gene's LOEUF score, 1.09, which puts it in group 4 of 6, group 1 being the genes least tolerant of losing a copy. Missense variants: 189 observed, 209.21 expected, observed/expected ratio (o/e) 0.9, 90% interval 0.8 to 1.02. Synonymous variants: 92 observed, 86.47 expected, observed/expected ratio (o/e) 1.06, 90% interval 0.9 to 1.26.
Homologues: Orthologues: macaque LCN8 (88% identical), dog LCN8 (75% identical), mouse Lcn8 (69% identical), rat Lcn8 (68% identical), guinea pig LCN8 (66% identical), pig LCN8 (63% identical), chimpanzee LCN8 (49% identical). Paralogues in human: LCN15 (20% identical), LCNL1 (19% identical), PTGDS (19% identical), LCN10 (18% identical), PAEP (18% identical), LCN12 (17% identical), LCN6 (17% identical), LCN1 (16% identical), LCN2 (15% identical), OBP2A (14% identical), LCN9 (13% identical), OBP2B (12% identical).
Diseases named in the same sentence as LCN8 in open-access papers:
LCN8 is named in the same sentence as 7 diseases in open-access papers, as found by Europe PMC text mining. Sharing a sentence is not in itself a finding about the gene and the disease. The quoted sentences say what the papers report.
Alzheimer disease (1 paper, 2024). A progressive, neurodegenerative disease characterized by loss of function and death of nerve cells in several areas of the brain leading to loss of cognitive function such as memory and language. "We found that NSUN7, SLC6A8, CXCL1 and LCN8 were significantly different in groups B compared to A, and SLC1A3 and LCN8 were significantly different in groups C compared to A. NSUN7, a m5C RNA methyltransferase gene, is differentially expressed in Alzheimer's disease patients." (PMID 39185136, 2024).
Autoimmunity (1 paper, 2024). The occurrence of an immune reaction against the organism's own cells or tissues. "However, recent research suggests LCN8 may be involved in allergen-induced immunity and autoimmunity." (PMID 39346910, 2024).
Infertility (1 paper, 2024). "In this study, we took advantage of the CRISPR/Cas9 system by knocking out the epididymis-enriched Lcn8/5/6/10/9 and Ly6g5b/c gene clusters and found infertility phenotypes." (PMID 36428102, 2024).
post-traumatic stress disorder (1 paper, 2024). An anxiety disorder precipitated by an experience of intense fear or horror while exposed to a traumatic (especially life-threatening) event. "LCN8, a member of the liposome protein family, was found to be associated with the severity of post-traumatic stress disorder symptoms by genome-wide DNA methylation analysis." (PMID 39185136, 2024).
teratospermia (1 paper, 2024). "Spermatogenesis and fertility were normal conditions after Lcn8 or Lcn9 inactivation in the epididymis, while Lcn8 ablation caused an increased teratospermia rate, sperm motility, and acrosome reaction frequency deficiency, indicating its indispensable role in sperm maturation." (PMID 38785936, 2024).
ZIKV infection (1 paper, 2021). "In this study, ZIKV infection resulted in significant downregulation of the Lcn gene clusters at transcriptional level and altered the distribution pattern of Lcn8 protein, especially in the IS region, which may be attributed to ZIKV-induced disruption of the epithelium." (PMID 33667230, 2021).
LCN8 also shares sentences with these, for which no sentence is quoted: tuberculosis (1 paper).